PPIAL4H (peptidylprolyl isomerase A like 4H)
Description:
PPIases accelerate the folding of proteins. It catalyzes the cis-trans isomerization of proline imidic peptide bonds in oligopeptides.
Gene: Protein-coding gene on chromosome 1 (146,344,006 to 146,344,765, reverse strand). Ensembl gene ENSG00000270339.
Subcellular location: Cytoplasm
Gene Ontology:
Molecular function: cyclosporin A binding; peptidyl-prolyl cis-trans isomerase activity
Biological process: protein folding
Cellular component: cytoplasm
Genetic constraint (gnomAD): Loss-of-function variants: 5 observed, 6.52 expected, observed/expected ratio (o/e) 0.77, 90% interval 0.4 to 1.57. That is too few expected variants to judge how well the gene tolerates losing a copy. Missense variants: 101 observed, 147.19 expected, observed/expected ratio (o/e) 0.69, 90% interval 0.58 to 0.81. Synonymous variants: 36 observed, 51.82 expected, observed/expected ratio (o/e) 0.69, 90% interval 0.53 to 0.92.
Homologues: Orthologues: zebrafish ppifa (68% identical), zebrafish ppiab (67% identical), Caenorhabditis elegans cyn-3 (65% identical), Caenorhabditis elegans cyn-7 (64% identical), zebrafish ppiaa (63% identical), Caenorhabditis elegans cyn-2 (62% identical), Caenorhabditis elegans cyn-1 (60% identical), Caenorhabditis elegans cyn-9 (49% identical), Drosophila melanogaster Cyp40 (48% identical), Drosophila melanogaster Moca-cyp (45% identical). Paralogues in human: PPIAL4C (98% identical), PPIAL4A (96% identical), PPIAL4E (96% identical), PPIAL4F (96% identical), PPIAL4G (96% identical), PPIAL4D (96% identical), PPIA (85% identical), PPIF (65% identical), PPIE (60% identical), PPID (59% identical), PPIB (55% identical), PPIC (52% identical), and 10 more.